ABCC8 (ATP binding cassette subfamily C member 8)
Description:
Regulator subunit of pancreatic ATP-sensitive potassium channel (KATP), playing a major role in the regulation of insulin release. In pancreatic cells, it forms KATP channels with KCNJ11; KCNJ11 forms the channel pore while ABCC8 is required for activation and regulation.
Synonyms: HRINS; SUR; SUR1; HI; PHHI; MRP8; ABC36; HHF1; TNDM2; MODY12; PNDM3; SUR1delta2
Tractability: Small molecule: an approved drug acts on it; a structure with a bound ligand is known; a high-quality ligand is known; it belongs to a druggable protein family. Antibody: UniProt places it where antibodies can reach, with high confidence; its Gene Ontology location is reachable by antibodies, with high confidence; UniProt predicts a signal peptide or a membrane-spanning region. PROTAC: ubiquitination databases record sites on it; a small molecule that binds it is known. Other modalities: a drug acting on it is in phase 2 or 3 trials.
Target class: ABCC subfamily; ATP-binding cassette; Transporter; Primary active transporter
Chemical probes: GLYBURIDE (high quality), REPAGLINIDE (high quality)
Safety:
Unwanted effects reported when the protein is acted on. In parentheses: how it was acted on, where the effect was seen, and who reports it.
abnormal pulse (activation, acute dosing; pancreas, renal, cardiovascular; source: Lynch et al. (2017))
atrioventricular block (inhibition, acute dosing; pancreas, renal, cardiovascular; source: Lynch et al. (2017))
cardiac arrhythmia (activation, acute dosing; pancreas, renal, cardiovascular; source: Lynch et al. (2017))
cardiac lesions (activation, acute dosing; pancreas, renal, cardiovascular; source: Lynch et al. (2017))
decreased blood glucose (inhibition, acute dosing; pancreas, renal, cardiovascular; source: Lynch et al. (2017))
decreased blood insulin (activation, acute dosing; pancreas, renal, cardiovascular; source: Lynch et al. (2017))
decreased blood pressure (activation, acute dosing; pancreas, renal, cardiovascular; source: Lynch et al. (2017))
decreased convulsions (activation, acute dosing; pancreas, renal, cardiovascular; source: Lynch et al. (2017))
decreased heart rate (inhibition, acute dosing; pancreas, renal, cardiovascular; source: Lynch et al. (2017))
increased blood insulin (inhibition, acute dosing; pancreas, renal, cardiovascular; source: Lynch et al. (2017))
increased heart rate (activation, acute dosing; pancreas, renal, cardiovascular; source: Lynch et al. (2017))
increased urinary sodium excretion (inhibition, acute dosing; pancreas, renal, cardiovascular; source: Lynch et al. (2017))
increased urine excretion (inhibition, acute dosing; pancreas, renal, cardiovascular; source: Lynch et al. (2017))
increased/decreased blood glucose (activation, acute dosing; pancreas, renal, cardiovascular; source: Lynch et al. (2017))
Gene: Protein-coding gene on chromosome 11 (17,392,498 to 17,476,894, reverse strand). Ensembl gene ENSG00000006071.
Subcellular location: Cell membrane
Subcellular location (Human Protein Atlas): Golgi apparatus; Nucleoli; Cytosol; Principal piece
Pathways (Reactome):
Disease: Defective ABCC8 can cause hypo- and hyper-glycemias
Metabolism: Regulation of insulin secretion
Neuronal System: ATP sensitive Potassium channels
Gene Ontology:
Molecular function: ATPase-coupled monoatomic cation transmembrane transporter activity; potassium channel activity; transmembrane transporter binding; ATP binding; ATP-activated inward rectifier potassium channel activity; ABC-type transporter activity; ADP binding; ATP hydrolysis activity; sulfonylurea receptor activity
Biological process: potassium ion import across plasma membrane; potassium ion transmembrane transport; potassium ion transport; regulation of insulin secretion; transmembrane transport; female pregnancy; intracellular glucose homeostasis; memory; negative regulation of angiogenesis; negative regulation of blood-brain barrier permeability; negative regulation of glial cell proliferation; negative regulation of insulin secretion; negative regulation of low-density lipoprotein particle clearance; negative regulation of neuroblast migration; negative regulation of neurogenesis; positive regulation of insulin secretion involved in cellular response to glucose stimulus; positive regulation of potassium ion transport; positive regulation of tight junction disassembly; positive regulation of tumor necrosis factor production; positive regulation of uterine smooth muscle relaxation; response to insulin; response to lipopolysaccharide; response to pH; response to xenobiotic stimulus; response to zinc ion; and 1 more
Cellular component: inward rectifying potassium channel; plasma membrane; potassium ion-transporting ATPase complex; membrane; presynaptic membrane; sarcolemma; synaptic vesicle membrane
Genetic constraint (gnomAD): Loss-of-function variants: 137 observed, 190.47 expected, observed/expected ratio (o/e) 0.72, 90% interval 0.62 to 0.83. The upper end of that interval is the gene's LOEUF score, 0.83, which puts it in group 3 of 6, group 1 being the genes least tolerant of losing a copy. Missense variants: 1,750 observed, 2,107.7 expected, observed/expected ratio (o/e) 0.83, 90% interval 0.8 to 0.86. Synonymous variants: 797 observed, 861.27 expected, observed/expected ratio (o/e) 0.93, 90% interval 0.87 to 0.98.
Gene-disease validity (ClinGen):
ClinGen rates the evidence that ABCC8 causes each of these diseases.
hyperinsulinemic hypoglycemia, familial, 1 (autosomal recessive): Definitive.
hyperinsulinism (autosomal dominant): Definitive. Abnormally high levels of insulin in the blood.
monogenic diabetes (semidominant): Definitive. Diabetes mellitus that is caused by mutations in a single gene.
pulmonary arterial hypertension (autosomal dominant): Moderate. Pulmonary arterial hypertension (PAH) is a group of diseases characterized by mean pulmonary artery pressure >20 mmHg and elevated pulmonary arterial resistance leading to right heart failure.
Homologues: Orthologues: chimpanzee ABCC8 (99% identical), macaque ABCC8 (99% identical), pig ABCC8 (97% identical), dog ABCC8 (96% identical), rat Abcc8 (96% identical), mouse Abcc8 (95% identical), guinea pig ABCC8 (93% identical), tropical clawed frog abcc8 (80% identical), zebrafish abcc8 (76% identical), zebrafish abcc8b (70% identical), Drosophila melanogaster MRP (30% identical), Drosophila melanogaster CG7627 (25% identical), and 9 more. Paralogues in human: ABCC9 (68% identical), ABCC1 (31% identical), ABCC3 (31% identical), ABCC2 (29% identical), ABCC6 (28% identical), ABCC10 (27% identical), ABCC4 (26% identical), ABCC5 (26% identical), ABCC12 (24% identical), ABCC11 (24% identical), CFTR (21% identical).
Diseases named in the same sentence as ABCC8 in open-access papers:
ABCC8 is named in the same sentence as 187 diseases in open-access papers, as found by Europe PMC text mining. Sharing a sentence is not in itself a finding about the gene and the disease. The quoted sentences say what the papers report.
diabetes (139 papers, 2007 to 2026). "The molecular characterization of KCNJ11 and ABCC8 mutations has arguably provided the most significant success story in precision medicine for diabetes." (PMID 41614934, 2026). "While GoF mutations cause diabetes via hyperpolarization, loss-of-function (LoF) mutations in ABCC8 or KCNJ11 traditionally result in the opposite phenotype: congenital hyperinsulinism (CHI)." (PMID 41614934, 2026). "Herein, we present a child (patient 53) who was diagnosed with hyperinsulinemic hypoglycemia at birth and then developed diabetes mellitus at the age of 10 years due to compound heterozygous variants (exon 23_28del and c.2329T > C (p.W777R)) of ABCC8." (PMID 39504571, 2025). "Variants in ABCC8 are known to cause several monogenic forms of diabetes, including permanent and transient forms of neonatal diabetes mellitus, and familial hyperinsulinaemic hypoglycaemia." (PMID 40210729, 2025). "The differential diagnosis initially considered other causes of neonatal diabetes, including transient neonatal diabetes mellitus (6q24 imprinting abnormalities) and monogenic forms of diabetes (KCNJ11/ABCC8 mutations)." (PMID 41393705, 2025). "Inactivating mutations in the ABCC8 gene have been reported to be associated with hyperinsulinemic hypoglycemia in infancy and diabetes later in life, particularly in individuals with biallelic variants in the ABCC8 gene." (PMID 39504571, 2025). "Recently, a study from China identified 17 rare ABCC8 variants among 543 individuals with early-onset-diabetes, of which only 8 variants were deemed to be pathogenic and cause ABCC8-MODY." (PMID 38980630, 2024). "The identification of ABCC8 mutations in patients clinically diagnosed with MODY has the ability to contribute to the precise management of diabetes." (PMID 39556225, 2024). "In 2 brothers with TNDM diagnosed with diabetes in 2010 (first observation period) and 2017 (second observation period) compound heterozygous variants of ABCC8 (NM_000352.6: c.4412-13G>A, p. ?; c.1619C>T, p.Thr540Ile) were detected." (PMID 38408297, 2024). "It is proven that autosomal dominant hyperinsulinism caused by LOF ABCC8 mutations develops reduced glucose tolerance and, in some cases, diabetes mellitus." (PMID 38791571, 2024). "Patients with heterozygous mutations in ABCC8 and their family members require long-term monitoring, as they are at increased risk of developing diabetes mellitus." (PMID 38791571, 2024). "The ABCC8 variants (p.L580_S581insFASL and p.S986⁣∗) found in two patients, respectively, were previously reported to be associated with diabetes." (PMID 40302972, 2024). "The functional consequences of ABCC8 mutations are extremely heterogeneous, ranging from neonatal hypoglycemia to early onset and late onset diabetes, with quite limited genotype-phenotype correlation." (PMID 38980630, 2024). "Because the MODY12 subtype is extremely rare in most populations, it is of interest to analyze variants in the ABCC8 gene in patients with diabetes mellitus." (PMID 36836406, 2023). "Variant c.1562G>A (p.Arg521Gln) in ABCC8 was detected in a compound heterozygous state with a pathogenic variant of the HNF1A gene in a diabetes patient and his mother." (PMID 36836406, 2023). "Known mutations in ABCC8 that cause diabetes mellitus either increase the activation of the Mg-nucleotide-mediated channel or alter the intrinsic gating." (PMID 36836406, 2023). "And we identified a positive selection signal for the ATP-binding cassette transporter subfamily C member 8 (ABCC8) gene on chromosome 11, a variant that causes hereditary diabetes and hyperinsulinemia." (PMID 36721228, 2023). "This indicates the need for long-term follow-up in patients with the ABCC8 gene mutations in view of the increased risk of diabetes later in life, and for a multidisciplinary approach due to multiple health problems from the neonatal period onwards." (PMID 36294341, 2022).
diabetes (continued). "Several switch genes, including AKT3, LAMA2, ADCY1, RAB3A, RAPGEF4, and ABCC8, have been implicated in insulin signaling and diabetes." (PMID 36389068, 2022). "Another study in a large cohort of nonobese patients with diagnosed age < 40 years and a family history of diabetes found 8 (8/1564, 0.5%) ABCC8 variants." (PMID 34631896, 2021). "Mice with the homozygous ABCC8 p.E1506K+/+ variant (an inactivating variant), presenting with hyperinsulinemia early in life followed by diabetes and early DKD later in life, were observed." (PMID 34631896, 2021). "According to the previous published studies reporting SUs on the treatment of ABCC8 variants induced diabetes, we found that 73.3% of the patients owing to ABCC8 variants with SUs got successful glucose control." (PMID 34631896, 2021). "This explains why pathogenic variants in ABCC8 have been widely related to diabetes mellitus and congenital hyperinsulinism." (PMID 34199176, 2021). "The first loss-of-function ABCC8 variant was a heterozygous inactivating ABCC8 p.E1506K variant, which presented with HH, followed by glucose intolerance and diabetes in later life." (PMID 34631896, 2021). "A study of people with hyperinsulinism caused by a heterozygous activating inactivating mutation in the ABCC8 gene, such as p.K1384Q and p.E1506K, discovered that the majority of the patients went on to develop diabetes later in life." (PMID 34584998, 2021). "There is added complexity associated with ABCC8 mutations, as compound heterozygosity for both an activating and an inactivating mutation can cause diabetes." (PMID 32027066, 2020). "Literature concerning follow-up of CH cases generally focuses only on diabetes secondary to surgery: in our cases two subjects showed diabetes after subtotal pancreasectomy and the other two were the two brothers of the B. family who had the ABCC8 mutation." (PMID 32928245, 2020). "Diabetes was observed in the heterozygous mother and a maternal uncle, but the father (V.1) who was also heterozygous for the ABCC8 mutation, had normal fasting plasma glucose and HbA1c levels." (PMID 29739729, 2019). "Regarding the type of mutation reported in ABCC8 which caused neonatal HH and diabetes later in life, only a few cases were reported to have a homozygous mutation, whilst the majority had heterozygous or compound heterozygous mutations." (PMID 29739729, 2019). "Herein, we present a patient with a novel homozygous ABCC8 mutation who was diagnosed with HH in the neonatal period and diabetes at the age of nine years." (PMID 29739729, 2019). "We now report two patients with diabetes diagnosed before 6 months of age: one with homozygosity for a novel ABCC8 nonsense variant and one with compound heterozygosity for the same nonsense variant and a previously reported loss-of-function missense mutation." (PMID 28663158, 2017). "Overall, we conclude that the syndromic diabetes presentation of the index case results from the combination of a heterozygous ABCC8-p.R825Q mutation causing diabetes and a homozygous CRYBB1-p.G71S mutation causing cataract." (PMID 29112131, 2017). "The ABCC8 gene is considered for genetic testing in neonatal diabetes but several studies have identified ABCC8 missense mutations in individuals with early and late onset diabetes." (PMID 29207974, 2017). "Case Report: We describe a case of a 9-week-old infant with neonatal diabetes who presented in diabetic ketoacidosis due to a mutation affecting the ABCC8 gene that encodes the SUR1 subunit of the potassium ATP channel." (PMID 28540314, 2017). "As for the genetic susceptibility for diabetes, ABCC8/KCNJ11 is associated with neonatal diabetes, GATA6 is associated with pancreas agenesis, and HNF1A is associated with monogenic diabetes." (PMID 28744848, 2017). "In the absence of extensive immunological and metabolic phenotyping of the patient and of heterozygous ABCC8 mutation carriers, we cannot however exclude the possibility of an autoimmune component to diabetes." (PMID 29112131, 2017).
diabetes (continued). "Noteworthy, the ABCC8-p.R825W mutation, affecting precisely the same amino-acid as the patient’s ABCC8-p.R825Q, has been associated with a very variable diabetes expressivity, ranging from neonatal diabetes to adult-onset diabetes and non-diabetic status." (PMID 29112131, 2017). "Prenatal testing is particularly relevant for the optimal management of diabetes in pregnant women with a mutation in one of the genes (KCNJ11 or ABCC8) encoding the potassium channel subunits." (PMID 27477181, 2017). "The fact that diabetes was relatively well controlled with low insulin doses when BMI was in the high range further argues for a causative ABCC8 mutation." (PMID 29112131, 2017). "Participants with six different genetic aetiologies were assessed, including two with a KCNJ11 or ABCC8 mutation, which account for >40% of all reported neonatal diabetes diagnoses." (PMID 28779213, 2017). "In our study group, all three patients who had diabetes subsequent to pancreatectomy had homozygous ABCC8 mutations." (PMID 26758964, 2016). "Gain-of-function mutations in either the Kir6.2 (KCNJ11) or SUR1 (ABCC8) subunits of the channel that impair the inhibitory effects of ATP cause a rare genetic form of diabetes that presents shortly after birth (permanent neonatal diabetes mellitus or PNDM)." (PMID 23626843, 2013). "This phenotypic spectrum of diabetes has also been reported in carriers of a mutation in ABCC8 or in the insulin (INS) gene, which both represent, with KCNJ11, the most frequently mutated genes in patients with NDM." (PMID 22701567, 2012). "Nevertheless, the occurrence of diabetes in young adults has recently been reported and is related to a heterozygous activating mutation of the ABCC8 gene encoding the sulphonylurea receptor 1 (SUR1)." (PMID 22284844, 2012). "For ABCC8, a rare mutation in ABCC8/SUR1 (ranked at 20) had been reported to have an effect on K(ATP) channel activity and beta-cell glucose sensing, leading to diabetes in adulthood." (PMID 21799737, 2011). "Activating mutations in ABCC8, which encodes for the outer subunit of the ATP-sensitive potassium channel (K-ATP channel), result in the inability to release insulin, leading to a form of monogenic diabetes with autosomal dominant transmission." (PMID 40003320, 2025). "Given the young age of onset of diabetes of probable genetic etiology, an NGS analysis of a panel of genes associated with monogenic diabetes was performed, which identified the c.638T>C [p.(Leu2132Pro)] variant in the ABCC8 gene, classified as probably pathogenic." (PMID 40003320, 2025). "Additionally, it should be mentioned that incretin-based therapy – and not sulfonylureas – has been shown to be an effective approach in individuals with diabetes owing to ABCC8 inactivating variants." (PMID 38980630, 2024). "Furthermore, patients with HI who carry dominantly inherited ABCC8 mutations occasionally develop diabetes later in life." (PMID 39556225, 2024). "Recent studies have shown that carriers of ABCC8 variants may develop diabetes during adulthood, even including homozygotes." (PMID 40302972, 2024). "While ABCC8 inactivation mutations typically cause a hypoglycemic phenotype, some dominant inherited mutations may lead to the development of diabetes in adulthood, supporting the hyperglycemic phenotype observed in proband B." (PMID 39556225, 2024). "Chronic β-cell hyperfunction turning into progressive exhaustion may be a putative mechanism for the hypoglycemia-diabetes duality observed with certain ABCC8 variants." (PMID 38980630, 2024). "In addition, heterozygous carriers of a mutation in the ABCC8 gene require long-term monitoring, as they present an increased risk for diabetes mellitus." (PMID 38791571, 2024).